NRCAM (neuronal cell adhesion molecule)
Diseases named in the same sentence as NRCAM in open-access papers (continued):
Sharing a sentence is not in itself a finding about the gene and the disease.
breast carcinoma (2 papers, 2011 to 2022). "All of these lines of evidence support the biological plausibility of our findings, suggesting that rs12539530, found in an ERE-related sequence and possibly regulating NRCAM expression, is associated with breast cancer susceptibility." (PMID 21281495, 2011). "Of the predicted ERE-related sequences found throughout the whole genome, the present study has identified a genetic variation of rs12539530, a SNP located in the putative ERE site in intron 2 of NRCAM, as an important factor in determining susceptibility to breast cancer development." (PMID 21281495, 2011). "A significant combined effect of rs12539530, an ERE SNP in intron 2 of NRCAM, which codes for a cell adhesion molecule, and SNPs of ESR1, the gene coding for ER, on breast cancer risk was found." (PMID 21281495, 2011). "Region 7q31, in which NRCAM is located, has never been reported to be important with regard to breast cancer risk determination in GWASs." (PMID 21281495, 2011). "Conversely, increased expression of NrCAM or CHL1 (a member of a homologous family) is correlated with better prognosis in prostate and breast cancer, both of which are hormone-related malignancies." (PMID 35388173, 2022). "In addition, expression of NRCAM, the gene putatively regulated by rs12539530, has been suggested to be upregulated in ER-positive, but not in ER-negative, breast cancer cell lines, and this hypothesis was confirmed by the present study." (PMID 21281495, 2011). "To this end, we checked the expression of NRCAM and PCDH17 in breast cancer cell lines expressing ESR1 (MCF-7 cells) or not expressing ESR1 (MDA-MB-231 cells) and examined whether the expression of these putative ER-regulated genes is ER-dependent." (PMID 21281495, 2011).
depression (2 papers, 2021). "Not only that, NrCAM functions at the neural plasticity, involving the theories of monoamine and neurotrophin in depression." (PMID 33912082, 2021).
gastric cancer (2 papers, 2022 to 2024). A primary or metastatic malignant neoplasm involving the stomach. "In an in vitro model of gastric cancer, the silencingof the NRCAM gene led to the inhibition of cell growth, migration,and invasion while promoting apoptosis." (PMID 38809962, 2024). "The results show that, compared with normal tissues, the expression of AGT and NrCAM in gastric cancer was significantly up-regulated while the expression of the other eight genes was down-regulated in gastric cancer." (PMID 35600357, 2022). "Therefore, we collected gastric cancer tissue samples for transcriptome analysis to further observe the expression of AGT and NRCAM in gastric cancer." (PMID 35600357, 2022). "After expression analysis and the observation of the expression in the stages of gastric cancer, we found that AGT and NrCAM were up-regulated in gastric cancer and that their appearance could increase with the increase of the stage." (PMID 35600357, 2022).
lung carcinoma (2 papers, 2013 to 2019). "ChIP-seq data from the ENCODE project indicate that both NRCAM and GPR56 contain binding sites for GRα, NF-κB and AP-1, while MEOX1 contain GRα and AP-1 sites in A549 lung cancer." (PMID 23593176, 2013). "On the other hand, NRCAM is clearly up-regulated in LUSC, entailing a promising marker to discriminate the two lung cancer types." (PMID 31429720, 2019).
multiple sclerosis (2 papers, 2020 to 2023). A progressive autoimmune disorder affecting the central nervous system resulting in demyelination. "Mutations in NrCAM that would affect such gelatinase cleavage sites have been shown to have profound effects on behavior, consistent with behavioral changes in multiple sclerosis." (PMID 37467333, 2023). "Its enhanced expression by astrocytes around inflammatory cuffs in EAE and detection of cleaved NrCAM in the CSF of patients with multiple sclerosis substantiate a role for this molecule at the astroglial border." (PMID 37467333, 2023). "Stainings for NrCAM showed similar patterns but were less intensive due to antibody quality; nevertheless, clear astrocyte NrCAM staining of some astrocytes was detected in multiple sclerosis samples." (PMID 37467333, 2023). "To define whether cleavage of VCAM-1 and NrCAM also play a role in human tissues, we analyzed the CSF of different patients with multiple sclerosis and age- and sex-matched, non-multiple sclerosis somatoform controls for gelatinase activity and the presence of soluble VCAM-1 or NrCAM." (PMID 37467333, 2023).
Obesity (2 papers, 2022 to 2023). Accumulation of substantial excess body fat. "In our study, Neuronal Cell adhesion molecule (NrCAM interactions) are highly expressed in both scz and obesity patient’s central nervous system(with a p-value of 0.00028)." (PMID 37494308, 2023). "CAM pathway’s present is also identical in obesity patient including NrCAM gene." (PMID 37494308, 2023). "However, in patients with normal weight and obesity NrCAM positively correlated with BMI before therapy which changed afterward." (PMID 36078974, 2022).
osteosarcoma (2 papers, 2022). A usually aggressive malignant bone-forming mesenchymal neoplasm, predominantly affecting adolescents and young adults. "After this, western blot analysis was adopted to assess the effect of KLF9 on NRCAM in the both osteosarcoma cells." (PMID 35399713, 2022). "The result manifested that NRCAM expression level was obviously diminished with high KLF9 expression in the both osteosarcoma cells." (PMID 35399713, 2022). "Afterwards, we determined that NRCAM was a direct target gene of miR-338-3p in osteosarcoma cells in accordance to bioinformatics methods and a dual luciferase assay." (PMID 35399713, 2022). "In this study, we verified that the expression level of miR-338-3p in osteosarcoma cell lines and tissues was downregulated and found that miR-338-3p suppressed the development and metastasis of osteosarcoma by targeting NRCAM directly." (PMID 35399713, 2022). "The result indicated that upregulation of miR-338-3p reduced the expression of NRCAM in the both osteosarcoma cells, and the overexpression of NRCAM was also blocked by miR-338-3p mimics." (PMID 35399713, 2022). "On the other hand, the outcomes also showed that elevated miR-338-3p expression level could suppress the proliferation, invasion and migration of osteosarcoma cells (P<0.05), and this influence could be rescued by NRCAM high-expression." (PMID 35399713, 2022). "In addition, we confirmed that the KLF9/ miR-338-3p/NRCAM axis yielded a critical effect on proliferation, invasion and migration in osteosarcoma." (PMID 35399713, 2022). "Furthermore, we also found that NRCAM had an enhanced effect on the proliferation, invasion and migration of osteosarcoma cells." (PMID 35399713, 2022). "These collective data showed that miR-338-3p could exert its function in osteosarcoma cells through blocking NRCAM." (PMID 35399713, 2022). "Furthermore, the result showed that overexpression of NRCAM could reduce the anti-tumor role of miR-338-3p in osteosarcoma cells." (PMID 35399713, 2022). "Interestingly, as for the six target genes, the result of qRT-PCR assay showed that the expression level of NRCAM was raised in MNNG/HOS and MG-63 cells than that in non-osteosarcoma cells." (PMID 35399713, 2022).
viral infection (2 papers, 2017 to 2020). "Significant NRCAM gene expression has been observed under specific circumstances, such as neuroinflammation triggered by influenza A long-term viral infection." (PMID 33301474, 2020).
Weaver syndrome (2 papers, 2013 to 2016). Weaver syndrome (WVS) is a rare, multisystem disorder characterized by tall stature, a typical facial appearance (hypertelorism, retrognathia) and variable intellectual disability. "NRCAM is expressed in the spinal cord and cerebellum which are both used for clinical validation of Weaver Syndrome." (PMID 23527149, 2013).
adrenal tumors (1 paper, 2019). "Likewise, patients with adrenal tumors had a significantly longer overall survival with NrCAM positive tissue (81.8 months vs. 60.9 months, p= 0.04)." (PMID 31989042, 2019). "Moreover, the survival analysis using subgroups revealed a significantly better overall survival for patients with NrCAM positive tumors in the subgroup of metastatic tumors as well as for patients with adrenal tumors." (PMID 31989042, 2019).
alcohol dependence (1 paper, 2018). Physical and psychological dependence on alcohol. "Relationships between markers in or near the NRCAM gene and drug or alcohol dependence were found in genome-wide linkage studies for alcoholism and early genome-wide association studies for drug dependence." (PMID 29675039, 2018).
astrocytoma (1 paper, 2019). "In contrast, in CNS tumors like astrocytoma as well as ependymoma, overexpression of L1 or NrCAM was correlated with a poor prognosis." (PMID 31989042, 2019).
brain tumors (1 paper, 2022). "An alternatively-spliced NRCAM isoform, shorter than the transcript we identified, was found to be specifically expressed in cell lines derived from human brain tumors and other human cancers." (PMID 36499391, 2022).
cataract (1 paper, 2021). Partial or complete opacity of the crystalline lens of one or both eyes that decreases visual acuity and eventually results in blindness. "NrCAM expression was reported to be essential for maintaining contact between lens cells, and a lack of NrCAM caused lens fiber disorder which ultimately led to the formation of mouse cataracts." (PMID 33771123, 2021).
cerebellar degeneration (1 paper, 2024). Degeneration of the cerebellum. "As classic A-T is characterized by cerebellar degeneration and abnormal saccadic eye movements, this finding suggests there may be an inverse association between expression of NRCAM and these A-T phenotypes." (PMID 38360726, 2024).
colorectal cancer (1 paper, 2023). A primary or metastatic malignant neoplasm that affects the colon or rectum. "NRCAM overexpression has previously been associated with vascular invasion in colorectal cancer." (PMID 37993901, 2023).
diabetes (1 paper, 2024). "The association between certain diagnostic genes, such as ITIH3 and NRCAM, and diabetes remains understudied." (PMID 39296548, 2024).
Down syndrome (1 paper, 2026). "DSCAM occupies a 1-Mb locus in the original Down syndrome critical region on chromosome 21q22 and encodes a neuronal cell adhesion molecule of importance for brain and eye development." (PMID 42063257, 2026).
drug dependence (1 paper, 2018). "Based on these findings, candidate gene approaches were used which found that NRCAM allelic variants were associated with drug dependence and methamphetamine dependence." (PMID 29675039, 2018).
dyslexia (1 paper, 2018). A learning disorder characterized by an impairment in processing written words. "Three CNVs were identified in genes that have been associated with dyslexia (CTNND2, NRCAM, and CNTNAP2) and their role in bone is currently unknown." (PMID 30042735, 2018).
endometriosis (1 paper, 2019). The growth of functional endometrial tissue in anatomic sites outside the uterine body. "For example, less than three publications have linked ITAC and NrCAM with a gynecological disorder other than endometriosis, and ENA78 has not been identified in any gynecological disease, including endometriosis." (PMID 31333337, 2019). "Nine of the proteins were identified as being statistically significant between the endometriosis patients and healthy controls with a p value < 0.05 [6Ckine, CD14, ENA-78, I-TAC, LAP (TGF-β), NrCAM, RAGE, TARC, TNF-β]." (PMID 31333337, 2019).
fetal growth restriction (1 paper, 2025). A fetus that does not grow beyond the 10th percentile of conventionally accepted weight for gestational age. "This study aimed to determine the association between NrCAM and fetal growth restriction and preeclampsia, including its potential as a biomarker." (PMID 40694862, 2025). "Circulating NrCAM is reduced with fetal growth restriction, and may be usful as a biomarker." (PMID 40694862, 2025).
Graves disease (1 paper, 2023). Graves' disease is an autoimmune disorder that leads to overactivity of the thyroid gland (hyperthyroidism).It is caused by an abnormal immune system response that causes the thyroid gland to produce too much thyroid hormones.
Headache (1 paper, 2024). Cephalgia, or pain sensed in various parts of the head, not confined to the area of distribution of any nerve. "NrCAM has been documented as influencing vulnerability to stress, for example regarding stress-induced headaches, stress-induced changes in pituitary function, and stress-induced changes in hippocampal neurogenesis." (PMID 38601326, 2024).
L1 syndrome (1 paper, 2022). L1 syndrome is a mild to severe congenital X-linked developmental disorder characterized by hydrocephalus of varying degrees of severity, intellectual deficit, spasticity of the legs, and adducted thumbs. "Finally, our structural and biochemical analysis indicated that L1 syndrome-associated mutations in L1CAM, a member of the L1 immunoglobulin family proteins including Nfasc, L1CAM, NrCAM, and CHL1, compromise binding with ankyrins." (PMID 35850303, 2022).
liver dysfunction (1 paper, 2022). "Apparently, NrCAM might be associated with liver dysfunction in psoriatic patients, which needs to be further elucidated." (PMID 36078974, 2022).
metastasis (1 paper, 2022). The spread or migration of cancer cells from one part of the body (where they first appeared) to another. "Moreover, we have validated some previously reported overexpressed genes such as TGFB1, IBSP, MMP9, or ITGB3 in bone metastasis; CRYAB, NRCAM, and SOX2 in brain metastasis; VEGF and IL6 in lung metastasis; and CYP4F3 in liver metastasis." (PMID 34051058, 2022).
osteoporosis (1 paper, 2022). A condition of reduced bone mass, with decreased cortical thickness and a decrease in the number and size of the trabeculae of cancellous bone (but normal chemical composition), resulting in increased fracture incidence. "NRCAM may modulate geometric parameters of the femoral neck and contribute to an improved understanding of osteoporosis and pathophysiological mechanisms." (PMID 36133435, 2022).
ovarian carcinoma (1 paper, 2009). A malignant neoplasm originating from the surface ovarian epithelium. "PPBP was a secreted protein found up-regulated in the mouse plasma, but not discovered in the ovarian cancer cell lines, while CD14 and NRCAM were cell surface proteins from the ovarian cancer cell lines, and were not quantified in mouse plasma." (PMID 19936259, 2009).
Parasomnia (1 paper, 2021). A clinically observable or self-reported abnormal behavior, experience, or physiological event that occurs in association with sleep, specific sleep stages, or sleep-wake transitions. "An immune-triggered phospho-tau formation has recently been shown in anti-IgLON5-related tauopathy, a parasomnia with bulbar dysfunction due to an autoantibody against a neuronal cell-adhesion molecule." (PMID 34442795, 2021).
peripheral nerve injury (1 paper, 2024). Injury to a peripheral nerve. "We identify NrCAM as a significant Rbfox1 target in injured DRGs after peripheral nerve injury." (PMID 38241164, 2024).
placental insufficiency (1 paper, 2025). Failure of the placenta to deliver an adequate supply of nutrients and oxygen to the fetus. "As placental insufficiency is often associated with continuous and chronic placental hypoxia, we measured NRCAM mRNA in hTSCs cultured in hypoxic (1% O2) or normoxic conditions (8% O2) for 48 h." (PMID 40694862, 2025). "The study also provides mechanistic evidence from trophoblast models, and a hypoxic mouse model that placental hypoxia reduces NrCAM expression, linking NrCAM dysregulation to pathophysiology of placental insufficiency." (PMID 40694862, 2025). "Future studies should explore whether NrCAM similarly influences trophoblast or immune cell function at the maternal–fetal interface to better elucidate its role in the development of placental insufficiency." (PMID 40694862, 2025). "This study investigated whether NrCAM can predict diseases of placental insufficiency." (PMID 40694862, 2025).
preeclampsia (1 paper, 2025). Preeclampsia is a hypertensive disorder of pregnancy that is characterized by new-onset hypertension with proteinuria presenting after 20 weeks of gestation, and depending on mild or severe forms may initially present with severe headache, visual disturbances, and hyperreflexia. "This study identified that Neuronal Cell Adhesion Molecule (NrCAM) as strongly associated with fetal growth restriction, and preeclampsia, in multiple, well-characterised clinical cohorts." (PMID 40694862, 2025). "We demonstrated a consistent reduction in circulating NrCAM with preeclampsia and FGR in multiple, large, well-characterised cohorts." (PMID 40694862, 2025). "Little is known about NrCAM's involvement in the placenta regarding fetal growth restriction, and preeclampsia." (PMID 40694862, 2025). "Circulating and placental NrCAM levels were measured in participants with preterm FGR or preeclampsia." (PMID 40694862, 2025). "We next measured circulating NrCAM in a cohort of women already diagnosed with preeclampsia from South Africa, The Preeclampsia Obstetric Adverse Events (PROVE) cohort." (PMID 40694862, 2025). "In the South Africa cohort, circulating NrCAM was reduced with preeclampsia (p = 0.03, AUC = 0.70, n = 27 preeclampsia, n = 15 control)." (PMID 40694862, 2025). "We next analysed whether NrCAM could predict those who will develop preeclampsia in the BUMPS cohort (Melbourne, Australia) collected at 36 weeks’ gestation." (PMID 40694862, 2025). "However, circulating NrCAM was reduced in a cohort of pregnancies already diagnosed with preterm preeclampsia (PROVE cohort from South Africa)." (PMID 40694862, 2025). "Circulating NrCAM was also measured in international cohorts: a UK high-risk cohort of women presenting with reduced fetal movements and delivered an FGR infant; a high-risk cohort from South Africa diagnosed with preeclampsia or eclampsia." (PMID 40694862, 2025). "Unsurprisingly therefore, PlGF outperformed NrCAM as a biomarker of preeclampsia." (PMID 40694862, 2025). "NrCAM was also assessed in pregnancies with preterm FGR or preeclampsia (<34 weeks gestation)." (PMID 40694862, 2025). "From these data, we suggest that NrCAM may not be useful as a predictive biomarker for term preeclampsia, but could have utility as a diagnostic biomarker." (PMID 40694862, 2025). "Placental NrCAM protein expression was decreased in placenta from 43 women who birthed a preterm FGR infant (p = 0.005), or with preterm preeclampsia (p = 0.0002), compared to 19 gestation-matched controls." (PMID 40694862, 2025). "Plasma NrCAM was assessed at 36 weeks’ gestation in women who later delivered FGR infants (<3rd centile birthweight), or developed preeclampsia at term." (PMID 40694862, 2025). "Placental NrCAM expression was lower in FGR (p = 0.0003, n = 23 FGR) and preeclampsia (p = 0.0003, n = 41 preeclampsia, n = 20 controls)." (PMID 40694862, 2025). "Circulating NrCAM was not altered in 24 women who were later diagnosed with preeclampsia, compared to 936 who did not (p = 0.11), an AUROC of 0.60." (PMID 40694862, 2025). "We measured NrCAM and NFASC expression in placentas complicated by FGR and/or preeclampsia." (PMID 40694862, 2025). "NRCAM mRNA expression was not significantly altered in placentas from participants who delivered an FGR infant or diagnosed with preterm preeclampsia compared to gestation-matched controls." (PMID 40694862, 2025). "However, circulating NrCAM levels were not altered at 36 weeks’ gestation in pregnant women later diagnosed with preeclampsia." (PMID 40694862, 2025).